PRDX2 (peroxiredoxin 2)
Diseases named in the same sentence as PRDX2 in open-access papers (continued):
Sharing a sentence is not in itself a finding about the gene and the disease.
colon carcinoma (16 papers, 2016 to 2024). "Taken together, these results indicate that PRDX2 expression is closely associated with CD133+CD44+ CCSCs in colon cancer." (PMID 33819194, 2021). "The high expression of PRDX2 was closely associated with CD133+CD44+ CCSCs in colon cancer." (PMID 33819194, 2021). "When the Hh pathway was inhibited in HT29 cells with the SMO inhibitor cyclopamine, reduced expression of stemness markers, such as CD44 and CD133, was observed, suggesting that Prdx2 may promote CSC-associated properties in colon cancer via the Hh/Gli1 signaling pathway." (PMID 27894099, 2016). "The inhibitory effect of PRDX2 knockdown on the Akt signaling pathway is also verified in lung and colon cancer cells." (PMID 39234629, 2024). "According to the literature, PRDX2 is highly expressed in head and neck cancers, colon cancer, anterior adenocarcinoma, and osteosarcoma." (PMID 38831394, 2024). "PRDX2 can regulate the oxidative stress of colon cancer cells through the Wnt/B-catenin signaling pathway and influence the oxidative stress of tumor by regulating some microRNAs." (PMID 36141135, 2022). "High expression of the antioxidant gene peroxiredoxin-2 (PRDX2) has been attributed to CD133+CD44+ cells and is associated with colon cancer CSC stemness." (PMID 36289675, 2022). "PRDX2 knockdown leads to the degradation of β-catenin and ultimately the inhibition of colon cancer cell growth." (PMID 34384442, 2021). "PRDX2 is highly expressed in CD133/CD44-positive colon cancer tissues and spheroid CD133+CD44+ CCSCs." (PMID 33819194, 2021). "In our present study, we demonstrated that PRDX2 is highly expressed in CD133/CD44-positive colon cancer tissues and spheroid CD133+CD44+ CCSCs." (PMID 33819194, 2021). "The results of our previous studies confirmed that the well-studied antioxidant gene peroxiredoxin-2 (PRDX2) promotes colon cancer progression." (PMID 33819194, 2021). "A recent study reported that PRDX2 plays roles in the stem cell maintaining via activating the Hedgehog pathway in colon cancer." (PMID 32908916, 2020). "More importantly, it has been revealed that PRDX2 regulates the resistance of colon cancer cells to 5-FU by regulating the Akt signaling pathway." (PMID 32337219, 2020). "We analyzed the distribution/localization of ANXA2 and PRDX2 in patient colon cancer tissue sections." (PMID 30959964, 2019). "PRDX2 is overexpressed in colon cancer and depletion of PRDX2 expression inhibits colon cancer cell growth." (PMID 28432271, 2017). "Our data also suggested that the PI3K/AKT signaling pathway links PRDX2 with 5-FU-induced apoptosis in colon cancer." (PMID 28432271, 2017). "To investigate the role of PRDX2 in colon cancer cells, we transfected PRDX2-shRNA-LV and NC-shRNA-LV into the HT-29 and HCT116 cell lines." (PMID 28432271, 2017). "We showed that knocking down PRDX2 in vitro facilitates cell death and apoptosis in colon cancer cells treated with 5-FU." (PMID 28432271, 2017). "PRDX2, is an important member of the ROS scavenging system, and exerts an anti-apoptotic effect on colon cancer cells." (PMID 28432271, 2017). "To ascertain the effect of PRDX2 knockdown in colon tumor growth, we examined the in vivo efficacy of 5-FU in mice bearing abdominal tumors that originated from HCT116-shPRDX2 or HCT116-shCont cells." (PMID 28432271, 2017). "Taken together, our results demonstrate that inhibiting PRDX2 expression promotes 5-FU-induced apoptosis in colon cancer cells via the PI3K/AKT signal pathway." (PMID 28432271, 2017). "We analyzed the cell apoptosis by flow cytometry and found that knocking down PRDX2 expression in FU-treated colon cancer cells markedly increased apoptosis and protein levels of cleaved PARP and caspase-3." (PMID 28432271, 2017). "In our study, we found that knockdown of PRDX2 expression promotes sensitivity to 5-FU in colon cancer cells." (PMID 28432271, 2017).
colon carcinoma (continued). "Collectively, our results suggest that PRDX2 depletion, combined with 5-FU, promotes cell apoptosis in colon cancer cells." (PMID 28432271, 2017). "Here, we depleted PRDX2 by PRDX2-shRNA-LV transduction in two colon cancer cell lines and found that in vitro PRDX2 knockdown facilitates cell death, and apoptosis in 5-FU-treated colon cancer cells." (PMID 28432271, 2017). "The data we present suggest that depletion of Prdx2 or Hh/Gli signaling would be beneficial for suppressing CSCs in the treatment of colon carcinoma." (PMID 27894099, 2016). "To further define the role of Prdx2 in the modulation of CSC-associated properties, we overexpressed Prdx2 with Prdx2-GFP-LV transduction in the SW620, HT29, and HCT116 human colon cancer cell lines." (PMID 27894099, 2016). "We found that overexpression of Prdx2 significantly increased the percentage of CD133+ cells in all three colon cancer cell lines." (PMID 27894099, 2016). "Prdx2 depletion gives rise to decreased cell proliferation and enhanced apoptosis in colon cancer cells." (PMID 27894099, 2016). "Redox status is a critical factor in the maintenance of CSCs, and the antioxidant enzyme Peroxiredoxin 2 (Prdx2) plays an important role in the development of colon cancer." (PMID 27894099, 2016). "Our current study shows that the protein level of Prdx2 is markedly increased in CD133+ colon cancer cells compared with CD133- cells." (PMID 27894099, 2016). "PRDX2 overexpression was shown to be closely correlated with CD133+CD44+ CCSCs in colon cancer." (PMID 33819194, 2021). "Furthermore, expression patterns of ANXA2 and PRDX2 in colon cancer sections revealed that the distribution of these two proteins is highly distinct." (PMID 30959964, 2019). "In our study, we used PRDX2-shRNA-LV to deplete PRDX2 expression in colon cancer cells." (PMID 28432271, 2017). "Furthermore, when PRDX2 was overexpressed in colon cancer cells, we found increased p-AKT protein expression and reduced Bcl-2/Bax protein expression." (PMID 28432271, 2017). "These in vivo results suggest that PRDX2 contributes to anticancer drug resistance and that decreasing the expression of PRDX2 in combination with 5-FU treatment reduces tumor development in colon cancer." (PMID 28432271, 2017). "Taken together, our study suggests that decreasing the expression of PRDX2 could be a promising strategy for increasing the sensitivity of colon cancer cells to 5-FU." (PMID 28432271, 2017). "In our study, we found that p-AKT protein levels were lower in PRDX2-depleted colon cancer cells." (PMID 28432271, 2017). "Prdx2 has been reported to be overexpressed in colon carcinomas compared with normal colon tissues." (PMID 27894099, 2016). "In our study, we reported that Prdx2 acts as a promotor of CSC properties in colon cancer." (PMID 27894099, 2016). "Importantly, the crucial stem cell function-inducing role of PRDX2 in CD133+CD44+ CCSCs may have important clinical implications for eradicating colon cancer." (PMID 33819194, 2021). "Furthermore, a recent study showed that PRDX2 was related to resistance to 5-Fluorouracil (5-FU), one of the most common chemotherapeutic agents, and the reduced levels of PRDX2 could contribute to increasing the sensitivity of 5-FU in colon cancer cells." (PMID 32908916, 2020). "To investigate whether PI3K/AKT contributes to PRDX2-induced drug resistance in colon cancer, we used immunohistochemistry to detect PRDX2 and p-AKT protein levels in tumor tissues and their corresponding normal colorectal mucosal tissues from 50 colon cancer patients." (PMID 28432271, 2017). "Therefore, decreasing the expression of PRDX2 could be a promising strategy for increasing the sensitivity of colon cancer cells to 5-FU." (PMID 28432271, 2017). "Therefore, we sought to explore the significance of Prdx2 in colon cancer stem cells." (PMID 27894099, 2016).
colon carcinoma (continued). "Based on the degree of staining, the protein expression of PRDX2 and PRDX4 was significantly higher in colon cancer tissues than in normal tissues." (PMID 36969053, 2023). "In the present study, to investigate the relationship between PRDX2 expression and CD133+CD44+ CCSCs, immunohistochemical (IHC) staining was conducted to determine the expression of PRDX2 in CD133(+)/CD44(+) and CD133(-)/CD44(-) colon cancer patients." (PMID 33819194, 2021). "PRDX2 and p-AKT protein expression were analyzed by immunohistochemistry technology in human colon carcinoma tissues." (PMID 28432271, 2017). "We found that PRDX2 and p-AKT were strongly expressed in the cytoplasm of colon cancer cells, and were weakly expressed in normal colon mucosal tissues." (PMID 28432271, 2017). "We treated shCont and shPRDX2 transfected colon cancer cells with 5-FU and found that apoptotic cells, C-PARP and caspase-3 protein expression increased markedly when PRDX2 was depleted." (PMID 28432271, 2017). "To clarify the correlation of Prdx2 and CSCs, we assessed protein levels of Prdx2 and CD133 in colon carcinoma tissues by measuring Integrated Optical Density (IOD)." (PMID 27894099, 2016). "Then, we detected Prdx2 and CD133 protein levels in human colon carcinoma samples from 10 patients with immunohistochemical assay and found higher expression in colon carcinoma tissues compared with adjacent normal tissues." (PMID 27894099, 2016). "A significant positive correlation (correlation coefficient = 0.7863, P < 0.05) was observed between Prdx2 and CD133 expression levels in colon carcinoma tissues from 10 patients." (PMID 27894099, 2016). "In our studies, we found a correlation between Prdx2 and CD133 at the protein expression level using immunohistochemical assays in human colon carcinoma tissues." (PMID 27894099, 2016). "In vitro knockdown of Prdx2 reduced the CD133+ population and sphere formation in the SW620, HT29, and HCT116 colon cancer cell lines." (PMID 27894099, 2016). "In the present study, we tested the expression of Prdx2 and CD133 in human colon cancer tissues and found a positive correlation between Prdx2 and CD133." (PMID 27894099, 2016). "Our previous study demonstrated that PRDX2 is overexpressed in colon cancer tissues compared to adjacent noncancerous tissues." (PMID 33819194, 2021). "The IHC results revealed that PRDX2 was highly expressed in colon cancer with liver metastasis (LM) compared to nonmetastatic tissues (NM) and matched normal colon tissues (MN)." (PMID 33819194, 2021). "Subsequently, we assessed whether the stem cell function-regulating role of PRDX2 in CD133+CD44+ CCSCs involves Wnt signaling and the EMT process which play crucial roles in colon cancer initiation, metastasis and stemness maintenance." (PMID 33819194, 2021). "To determine the role of PRDX2 in colon cancer cells treated with 5-FU, we used the CCK-8 assay to detect the survival rate of colon cancer cells that were stably transfected with NC-shRNA-LV and PRDX2-shRNA-LV and treated with 5-FU at different concentrations for 48 h." (PMID 28432271, 2017). "Peroxiredoxin-2 (PRDX2), is an important member of the ROS scavenging system, and may be a potential target that promotes chemosensitivity to 5-FU in colon cancer." (PMID 28432271, 2017). "In our study, Prdx2, SMO, Gli1, and CD133 expression was verified in the colon cancer cell lines." (PMID 27894099, 2016). "However, as an important member of the ROS scavenging system, the contributions of Prdx2 to the maintenance of CSCs specifically involved in colon cancer have not been clearly defined." (PMID 27894099, 2016). "In addition, we further analyzed whether PRDX2 transcriptional levels correlate with CD133 and CD44 expression in 40 pairs of human colon carcinomas with matched adjacent noncancerous tissues (ANTs)." (PMID 33819194, 2021).
lung carcinoma (16 papers, 2017 to 2023). "The high levels of PRDX2 were associated with bad prognosis in lung cancer patients, especially in patients with adenocarcinoma." (PMID 32908916, 2020). "We investigated the association between PRDX2 levels and the prognosis of lung cancer patients." (PMID 32908916, 2020). "In lung cancer, nitrosylation of Cys51 and Cys172 of peroxiredoxin-2 (Prdx2)—an antioxidant enzyme that protects tumor cells from toxic level of H2O2—impairs the formation of Prdx2/Prdx2 homodimers, repressing its antioxidant activity." (PMID 34947954, 2021). "Previous study reveals that PRDX2 nitrosation regulated by GSNO can cause intracellular H2O2 accumulation and induce lung cancer cell death." (PMID 32337219, 2020). "To further examine the potential effects of PRDX2 in lung cancer cells, we analyzed the expression levels of PRDX2 in human normal bronchial epithelial cell line (BEAS-2B) and commonly used NSCLC cell lines (NCI-H460, NCI-H1650, NCI-H1299, and A549)." (PMID 32908916, 2020). "The results suggested that higher PRDX2 expression was significantly correlated with worse OS (P < 0.001), in 1925 lung cancer patients (967 samples with low PRDX2 expression and 958 samples with high PRDX2 expression)." (PMID 32908916, 2020). "Our data indicates that PRDX2 functions as a protumor regulator and is involved in tumorigenesis and tumor progression of lung cancer." (PMID 32908916, 2020). "Next, to better assess the role of PRDX2 played on clinical relevance in patients with lung cancer, we investigated the relationship between the levels of PRDX2 and the survival of lung cancer patients." (PMID 32908916, 2020). "We used the Kaplan–Meier plotter to analyze the survival of different levels of PRDX2 in lung cancer patients." (PMID 32908916, 2020). "To investigate the biological function of PRDX2 in lung cancer, we knocked down PRDX2 using two shRNAs and reveled that silencing PRDX2 expression inhibited cell proliferation, migration, and invasion in NSCLC cell line A549 cells." (PMID 32908916, 2020). "The lung has been proposed to have pro-oxidant environment due to high oxygen and toxins exposure, and anti-oxidative mediators such as NRF2, peroxiredoxin 2 and thioredoxin-like 2 stimulate the progression of lung cancer and lung metastasis." (PMID 30912515, 2019). "To validate this, we examined Prdx2 expression and its nitrosylation in lung cancer cells after GSNO treatment." (PMID 30988280, 2019). "Our studies showed that, as an endogenous NO carrier, S-nitrosoglutathione (GSNO) induced apoptosis in lung cancer cells via nitrosylating Prdx2." (PMID 30988280, 2019). "α-1-microglobulin/bikunin precursor (AMBP), peroxiredoxin 2 (PRDX2), and Parkinson’s disease protein 7 (PARK7) are three protein markers associated with lung cancers." (PMID 29597315, 2018). "As in the QDEM-based analysis, the concentrations of AMBP and PRDX2 markers in the lung cancer group were found to be higher than in the control group (FCs of 5.30 and 2.62, respectively), whereas PARK7 concentration was lower (FC = 0.36)." (PMID 28300171, 2017). "Higher concentrations of AMBP and PRDX2 markers were found in the lung cancer group compared to the control group (with a fold change (FC) of 3.4 and 2.0, respectively), whereas PARK7 concentration was lower (FC = 0.49)." (PMID 28300171, 2017). "Here, we present a novel suspension microarray for multiplexed analysis of three protein markers associated with lung cancer: α-1-microglobulin/bikunin precursor (AMBP), peroxiredoxin 2 (PRDX2), and Parkinson disease protein 7 (PARK7)." (PMID 28300171, 2017). "Here, the high levels of PRDX2 were associated with poor OS and PFS of patients with lung cancer." (PMID 32908916, 2020). "Similarly, the increased expression of PRDX2 was remarkably associated with progression-free survival (PFS) (P < 0.0001), in 982 patients with lung cancer (491 samples with low PRDX2 expression and 491 samples with high PRDX2 expression)." (PMID 32908916, 2020).
lung carcinoma (continued). "There is now increasing evidence that PRDX2 expression was significantly increased and may become a prognostic and therapeutic target in lung cancer." (PMID 32908916, 2020). "However, Prdx2 has been shown to increase nodal metastasis in lung cancer cells, and a positive correlation between Prdx2 and chemoresistance in breast and pancreatic cancer has been reported." (PMID 33182509, 2020). "Herein, we hypothesize that PRDX2 may have powerful effects on the tumor progression of lung cancer." (PMID 32908916, 2020). "Taken together, our results elucidate the roles and mechanisms of Prdx2 S-nitrosylation at Cys51 and Cys172 sites in lung cancer cells apoptosis and this finding provides an effective lung cancer treatment strategy for managing aberrant Prdx2 activity in lung cancers." (PMID 30988280, 2019). "Therefore, to regulate Prdx2 activity through posttranslational modification is an alternative way to inhibit lung cancer cell growth." (PMID 30988280, 2019). "In this study, we reported that GSNO induced lung cancer cell apoptosis via Prdx2 and AMPK pathway." (PMID 30988280, 2019). "In summary, our study demonstrates that GSNO could induce lung cancer cell apoptosis via nitrosylating Prdx2 to induce H2O2 accumulation, subsequently increasing AMPK phosphorylation and further inhibiting the activity of SIRT1." (PMID 30988280, 2019). "In addition, lower PRDX2 expression was associated with less pulmonary metastasis nodules, suggesting that PRDX2 might promote the metastasis of lung cancer." (PMID 32908916, 2020). "PRDX2 may potentially become a novel therapeutic target for lung cancer." (PMID 32908916, 2020). "Therefore, it should be valuable to explore whether GSNO can regulate Prdx2 activity by nitrosylation and further induce the apoptosis of lung cancer cells." (PMID 30988280, 2019). "In lung cancer cells, S-nitrosylation of the H2O2-eliminating enzyme Prdx2 (peroxiredoxin-2) led to increases in H2O2 levels, which activated AMPK, followed by phosphorylation of SIRT1 and, thus, abolishment of its deacetylating activity." (PMID 34279445, 2021). "This study showed that PRDX2 is highly expressed in lung cancer, and it is correlated with worse OS and PFS of lung cancer patients." (PMID 32908916, 2020). "The mRNA levels of PRDX1, PRDX2, PRDX3, PRDX5, and PRDX6 showed an excellent correlation with the OS of lung cancer patients." (PMID 32908916, 2020). "Since silencing PRDX2 expression repressed the malignancy of lung cancer, we next transfected NCI-H1299 cells with PRDX2 overexpressed or controlled plasmids for 72 hours." (PMID 32908916, 2020). "The statistical results of the preclinical validation of the QDEM and xMAP® 3-plex immunoassays detecting AMBP, PRDX2, and PARK7 markers as tools for diagnosis of lung cancer were practically identical." (PMID 28300171, 2017). "In order to compare QDEM and xMAP® technologies, the same 3-plex immunoassay for the quantification of AMBP, PRDX2, and PARK7 lung cancer markers was developed for xMAP®." (PMID 28300171, 2017). "However, there are some limitations and shortcomings in this study: we did not investigate the correlation of PRDX2 expression and tumor growth or metastasis of lung cancer patients." (PMID 32908916, 2020). "However, the correlation between the levels of PRDX2 and the initiation of lung cancer has not been assessed yet." (PMID 32908916, 2020).